E2F7 (E2F transcription factor 7)
Diseases named in the same sentence as E2F7 in open-access papers (continued):
Sharing a sentence is not in itself a finding about the gene and the disease.
neuroblastoma (4 papers, 2022 to 2024). Neuroblastoma (NB) is the most common solid, extracranial childhood tumor. "E2F transcription factors E2F1, E2F3, E2F7 and E2F8 were all associated with the event free survival of neuroblastoma in TARGET, GSE16476 and GSE85047 datasets." (PMID 35764946, 2022). "In addition, inhibition of exportin one led to E2F7 nuclear accumulation, blocking neuroblastoma progression." (PMID 39613162, 2024). "By directly binding to and altering the subcellular distribution of cytoplasmic E2F7, suppressor anaphase-promoting complex domain 2 (SAPCD2) promotes neuroblastoma progression by modulating E2F activity and affecting genes involved in the cell cycle and chromosomal instability." (PMID 38992083, 2024).
non-small cell lung carcinoma (4 papers, 2020 to 2024). A group of at least three distinct histological types of lung cancer, including non-small cell squamous cell carcinoma, adenocarcinoma, and large cell carcinoma. "Although E2F7 has been reported to act as a tumor suppressor in murine skin cancer and liver cancer, other data are consistent with its oncogenic role in murine non-small cell lung cancer and several other human cancers." (PMID 39613162, 2024). "Additionally, our results revealed that SNHG7 and E2F7 were upregulated, while miR-181a-5p is underexpressed in non-small-cell lung cancer." (PMID 35383161, 2022).
lung squamous cell carcinoma (3 papers, 2018 to 2024). "The transcriptional levels of E2F7 in squamous cell lung carcinoma (fold change = 7.296) and in large-cell lung carcinoma (with fold change = 4.243) significantly differ from those in the normal samples in Hou’s dataset." (PMID 29754146, 2018). "The results showed that E2F7 is highly expressed in LUAD, lung squamous cell carcinoma (LUSC), esophageal squamous cell carcinoma (ESCA) and other solid tumors." (PMID 35984189, 2022).
melanoma (3 papers, 2020 to 2025). A malignant, usually aggressive tumor composed of atypical, neoplastic melanocytes. "Among down-regulated genes, the analysis showed several experimentally validated target genes, such as E2F7, MAP2K1 (also known as MEK1), CCNG1, HMGB2, SIRT1, belonging to key signaling pathways frequently associated to melanoma." (PMID 33670365, 2021). "The expression levels of E2F2, E2F7, and E2F8 in the C4 melanoma cell subgroup were significantly higher compared to other subgroups." (PMID 39781353, 2025).
ovarian carcinoma (3 papers, 2009 to 2016). A malignant neoplasm originating from the surface ovarian epithelium. "However, another study indicated that down-regulation of E2F7 may contribute to mechanisms underlying platinum resistance in 77 ovarian cancer patients." (PMID 26397135, 2015). "High E2F7 expression was shown to improve clinical outcomes and was a favorable disease-free survival factor in ovarian cancer, indicating that E2F7 improve the prognosis of ovarian cancer." (PMID 26824182, 2016). "Some reports have linked abnormal expression of E2F7 with cancer, for instance, increased E2F7 expression in cutaneous SCC and its decreased expression in ovarian cancer." (PMID 26397135, 2015). "E2F2 and E2F7 are overexpressed where the first is shown to be an activator and considered as an oncogene, overexpressed in large size and aggressive ovarian cancers." (PMID 19662092, 2009).
thyroid cancer (3 papers, 2022 to 2023). "We defined 210 genes as the minimum core of E2F7-mediated transcription program guiding the progression of thyroid cancer cells towards a more aggressive phenotype." (PMID 36765037, 2023). "To consolidate these data, we evaluated E2F7 expression in thyroid cancer-derived cell lines, using the CellMinerCDB database." (PMID 36765037, 2023). "Moreover, Zhou and colleagues found a correlation between high levels of E2F7 and poor disease-free survival in thyroid cancer patients and demonstrated that E2F7 silencing restrain proliferation of PTC cell lines." (PMID 36765037, 2023). "Several transcription factors including E2F7, FOXM1, NFYB, and CREB3L1 were significantly associated with the OS of thyroid cancer patients and may be the main regulators of ATC progression." (PMID 36192735, 2022).
acute myeloid leukaemia (2 papers, 2021 to 2022). "In addition, E2F7 has been found up-regulated in various malignant tumors, such as acute myeloid leukaemia and cutaneous squamous cell carcinomas." (PMID 34416861, 2021).
cutaneous squamous cell carcinoma (2 papers, 2015 to 2021). "Previous study identified that E2F7 was overexpressed in cutaneous squamous cell carcinomas (SCC), and could suppress proliferation and apoptotic responses." (PMID 26397135, 2015).
nasopharyngeal carcinoma (2 papers, 2023 to 2025). A carcinoma arising from the nasopharyngeal epithelium. "VIRMA can up-regulate the expression of E2F7 and maintain the stability of E2F7 mRNA, promoting the occurrence and metastasis of nasopharyngeal carcinoma." (PMID 41256854, 2025).
ocular melanoma (2 papers, 2024). A melanoma that arises from the structures of the eye or ocular adnexa. "Furthermore, the application of a nanodrug containing miR-30a-5p has demonstrated the ability to suppress malignant characteristics of ocular melanoma through targeted interaction with E2F7, as observed in both laboratory and live settings." (PMID 39590378, 2024).
osteosarcoma (2 papers, 2018 to 2022). A usually aggressive malignant bone-forming mesenchymal neoplasm, predominantly affecting adolescents and young adults. "In osteosarcoma, upregulation of ATF6 and E2F7 during sustained ERS suppressed E2F1 expression, upregulation of E2F7 was dependent on activation of XBP1, and downregulation of E2F1 enhanced Noxa and Puma expression and promoted ER stress-induced apoptosis." (PMID 36551309, 2022).
anaplastic cancer (1 paper, 2023). "This contrasts with the onco-suppressive role of E2F7 described in other settings, opening the possibility to reconsider its activity in anaplastic cancers." (PMID 36765037, 2023).
astrocytoma (1 paper, 2025). "Many studies on MYBL2, E2F7, CCN4, and MET genes promote tumor progression by promoting tumor proliferation, differentiation, and migration, which may also contribute to the malignant progression of IDH-mutant astrocytoma." (PMID 41460424, 2025).
bladder cancer (1 paper, 2022). "Previous evidence has established that E2F7 transcriptional factor plays an essential role in the regulation of cell cycle progression; FOXM1 encoded protein is activated in M phase and has been validated as an essential transcriptional factor playing roles in bladder cancer progression." (PMID 35879690, 2022).
COVID-19 (1 paper, 2025). A disease caused by infection with severe acute respiratory syndrome coronavirus 2. "Among the ten candidate hub genes, we found that 8 hub genes were differentially upregulated in HBV and COVID-19, so we further narrowed the scope of the study to 8 hub genes, including CDK1, E2F7, E2F8, TYMS, KIF20A, CENPE, TPX2, HMMR." (PMID 40408617, 2025). "SARS-CoV-2 also exploits the host cell cycle machinery to facilitate viral replication, suggesting that E2F7 and E2F8 may play a role in COVID-19 pathogenesis by modulating cell cycle and DNA repair pathways." (PMID 40408617, 2025).
gastric intestinal type adenocarcinoma (1 paper, 2021). An adenocarcinoma of the stomach arising on a background of intestinal metaplasia. "Furthermore, E2F7 was upregulated in GC (fold change = 1.977, p = 3.93E-05) and gastric intestinal-type adenocarcinoma (fold change = 3.234, p = 3.39E-07)." (PMID 34532281, 2021).
Giardia infection (1 paper, 2023). "Hence, we speculate that E2F1 may be regulated by E2F7 and E2F8 during Giardia infection, although the precise mechanism is still unknown." (PMID 37006313, 2023).
hepatic diseases (1 paper, 2023). "E2F7 has been previously found to inhibit liver tumor growth and through regulation of polyploidy also be involved in different hepatic diseases." (PMID 37415213, 2023).
lentivirus infection (1 paper, 2020). Virus diseases caused by the Lentivirus genus. "To verify this, we employed lentivirus infection and verify the radioresistance role of E2F7 both in vitro and in vivo." (PMID 32064771, 2020).
liver cirrhosis (1 paper, 2022). "Whereas, the ascent of E2F7 in tumor tissues was significantly correlated with the parameters associated with dismal prognosis and outcome, such as larger tumor diameters, advanced tumor node metastasis classification stages, tumor microsatellite, venous invasion, and severe liver cirrhosis." (PMID 35924788, 2022).
medullary thyroid carcinomas (1 paper, 2021). "Pathological analysis revealed that four out of the five Rb+/−7−/− tumor lesions were medullary thyroid carcinomas, suggesting that loss of E2F7 aggravates the malignant progression of Rb-deficient thyroid tumors." (PMID 33922435, 2021).
oral squamous cell carcinoma (1 paper, 2021). "Nevertheless, little has been reported about the impacts of E2F7 on oral squamous cell carcinoma (OSCC)." (PMID 33637098, 2021).
pituitary tumor (1 paper, 2021). A benign or malignant neoplasm affecting the pituitary gland. "In contrast, loss of either E2f7 or E2f8 largely prevented the formation of pituitary tumors in Rb+/− mice." (PMID 33922435, 2021). "Surprisingly, additional deletion of E2f7 or E2f8 resulted in significantly lower pituitary tumor incidence compared to Rb+/− mice." (PMID 33922435, 2021). "This checkpoint-based hypothesis does not explain our observations that E2f7 or E2f8 deletion prevented pituitary tumor formation in the Rb+/− model." (PMID 33922435, 2021).
skin aging (1 paper, 2021). The gradual irreversible changes in structure of skin that occur as a result of the passage of time.. "The TF E2F7 was also regulated by protein AIFM1 to downregulate target gene APAF1 in both young-adult and middle-aged skin aging." (PMID 34073305, 2021).
skin cancer (1 paper, 2011). "Both E2F1 and E2F7 are significantly overexpressed in transformed keratinocytes and there is evidence that the dysregulation of expression of the E2F1 and E2F7 isoforms may contribute to skin cancer formation." (PMID 22272113, 2011).
small cell lung carcinoma (1 paper, 2024). Small cell lung cancer (SCLC) is a highly aggressive malignant neoplasm, accounting for 10-15% of lung cancer cases, characterized byrapid growth, and early metastasis. "Additionally, E2F7's close association with the metastasis of small cell lung cancer has been documented." (PMID 38760774, 2024).
tumor (80 papers, 2009 to 2026). "Cross comparison of our DEGs to a E2F1 cistrome revealed many E2F1 target genes (E2f7, Rtel1, Myc, Ybx3 and Id3) being downregulated in β1 integrin-deficient tumours, consistent with slow tumour growth phenotype." (PMID 34782719, 2022). "Higher expression of E2F7 was significantly linked with higher tumor grade (P < .001), wild type (WT) of IDH (P < .001) and unmethylation status of MGMT promoter (P < .001)." (PMID 32064771, 2020). "It has been reported that E2F7 is implicated in cell cycle and proliferation of tumor cells under the regulation of miRNA." (PMID 33201900, 2020). "Furthermore, E2F7 was found to be significantly associated with poor prognosis, tumor progression, and drug resistance in PCa." (PMID 39590378, 2024). "E2F 7/8 were also identified as significantly associated with tumor stage in the GEPIA database." (PMID 38241554, 2024). "However, E2F7 expression was significantly associated with tumor grade (p = 0.041) and strongly associated with distant relapse free survival (p = 0.007)." (PMID 26397135, 2015). "The E2F family of transcription factors, particularly E2F1 and E2F7 which are often upregulated in tumors, are master regulators of cell cycle progression and are known to enhance tumor cell proliferation, angiogenesis, and invasiveness." (PMID 41584032, 2026). "Taken together, miR-5100 replacement significantly rescues the tumor-promoting effects of E2F7 overexpression by directly targeting E2F7 3′-UTR in PCa cells." (PMID 39590378, 2024). "Overall, our inquiry has revealed an unacknowledged role of miR-5100 in inhibiting tumor growth in PCa via affecting the cell cycle and targeting E2F7." (PMID 39590378, 2024). "E2F7 is reported to be a tumor promoter in BC, inducing cancer cell proliferation, invasion, and metastasis." (PMID 38073330, 2024). "In another set of experiments, IHC staining detected high expression of E2F7 in the tumor areas of patients with LUAD, consistent with bioinformatics analysis results." (PMID 38760774, 2024). "Knockdown of E2F7 significantly inhibited tumor development, as indicated by the reduced weight of shE2F7 tumors compared to the control." (PMID 38760774, 2024). "To evaluate the effects of MYBL2 knockdown on E2F1 overexpression or E2F7 knockdown in a more physiologically relevant setting, we performed tumor xenograft assays using genetically modified AGS sublines generated using the Tet-On system." (PMID 39613162, 2024). "E2F7 knockdown led to increases in tumor volume, tumor weight, tumor growth, Ki67-positive cells, and earlier tumor onset, all of which were attenuated by MYBL2 knockdown." (PMID 39613162, 2024). "After sh-circFKBP8#1 transduction, the expression of circFKBP8 and E2F7 mRNA was remarkably decreased, but miR-432-5p expression was increased in tumor tissues." (PMID 39192374, 2024). "Correlations between E2F expression and tumor stage in LUAD patients were also analyzed and we found that those of E2F7/8 were significantly associated with tumor stage (P < .05), while those of E2F1/2/3/4/5/6 were not (P > .05)." (PMID 38241554, 2024). "For its role in promoting sensitivity to anti-cancer drugs and in inhibiting angiogenesis E2F7 is primarily acknowledged as tumor suppressor." (PMID 36765037, 2023). "Protein-coding genes with increased expression across all tumor types included E2F7, ETS1, EZH2, ID3/4, MKI67, PIK3R3, and TOP2A." (PMID 36865335, 2023). "In this study, we observed that E2F7 was highly expressed in both HCC tumor tissues and cells, and presented an inverted correlation with the PFS and OS of the patients." (PMID 35924788, 2022).
tumor (continued). "We constructed cell lines that overexpressed circLATS2 and miR-520a-3p, as well as overexpressed circLATS2 and knockdown E2F7, and verified their effects on the proliferation and invasion of tumor cells through CCK8 and Transwell assay." (PMID 35444695, 2022). "Among the complex functions in the tumor cell, E2F7 exerts the repressive translational regulation on miR‐383‐5p." (PMID 35924788, 2022). "For tumor tissues, we observed that 72.4% (63/87) of the cases showed E2F7 expression and the rest 27.6% (24/87) ones with a relatively lower Anillin expression." (PMID 35924788, 2022). "Accordingly, we detected and observed an obvious upregulation of E2F7 in both HCC tumor tissues and cells, positively correlated with SP1, SOX4, and Anillin." (PMID 35924788, 2022). "The quantification of the orthotopically transplanted masses in the liver was measured 6 weeks postorthotopic injection of the transfected Hep3B cells, and the result demonstrated much smaller tumor masses generated in mouse livers when E2F7 was depleted." (PMID 35924788, 2022). "Univariate Cox regression results show T stage (P = .002), N stage (P < .001), M stage (P = .006), pathologic stage (P < .001), primary therapy outcome (P < .001), residual tumor (P < .001) and E2F7 (P = .002) were significantly related to poor prognosis." (PMID 35984189, 2022). "We used the Timmer database to perform pan-tumor E2F7 expression analysis and showed that E2F7 is highly expressed in a variety of solid tumors including LUAD." (PMID 35984189, 2022). "Further multivariate Cox analysis confirmed that pathologic stage (P = .040), primary therapy outcome (P < .001), residual tumor (P = .001) and E2F7 (P = .027) are independent factors affecting the prognosis of LUAD patients." (PMID 35984189, 2022). "As a tumor-accelerating transcriptional factor, E2F transcription factor 7 (E2F7) was up-regulated in many forms of cancers." (PMID 33637098, 2021). "Among many types of malignancies, E2F7 is frequently up-regulated, thus it is a tumor-promoting transcription factor." (PMID 33637098, 2021). "We demonstrated previously that E2F7 and −8 suppress tumor growth in the liver via transcriptional repression of E2F targets and possibly through promoting polyploidization." (PMID 33922435, 2021). "We found that E2F7 expression was higher in the majority of OSCC tissues (n = 340) than in the non-tumor samples (n = 32) (p < 0.0001)." (PMID 33637098, 2021). "Six weeks later, E2F7 knockdown reduced tumor volume and weight, which was negated following dual treatment with shE2F7 and MAPK." (PMID 33489876, 2020). "In the subcutaneous tumour model, E2F7 silencing had significantly inhibited tumour growth compared with control groups, and this effect was rescued by the EZH2 overexpression." (PMID 32814835, 2020). "The E2F7 expression was remarkably positively related to tumor purity (r = 0.344, P = 3.54e − 05) in GBM." (PMID 33381564, 2020). "The E2F7 gene, located at chromosome 12q21.2, contains 14 exons and acts as a tumor suppressor in the regulation of cell cycle progression." (PMID 32117628, 2020). "Correlation analysis suggested a remarkable negative correlation between E2F7 and miR-424-5p, and E2F7 was highly expressed in HCC tumor tissue." (PMID 33201900, 2020). "E2F7 expression level in LGG showed a positive correlation with tumor purity and infiltrating levels of B cells, CD8+ T cells, macrophages, and dendritic cells." (PMID 33381564, 2020). "E2F transcription factor 7 (E2F7) exerts tumor suppressive role by suppressing the transcription level of genes that participated in the entry of S-phase and disease progression." (PMID 33489876, 2020). "MYLK-AS1 promoted HCC tumor angiogenesis and cell proliferation in vitro and in vivo by directly targeting miR-424-5p to upregulate E2F7 and activate VEGFR-2 signaling, consequently promoting the HCC progression." (PMID 33168027, 2020).